CBLC (Cbl proto-oncogene C)
Diseases named in the same sentence as CBLC in open-access papers (continued):
Sharing a sentence is not in itself a finding about the gene and the disease.
infection (1 paper, 2025). The state of being infected such as from the introduction of a foreign agent such as serum, vaccine, antigenic substance or organism. "This suggests that patients with cblC deficiency complicated with PH commonly present with symptoms of hypoxia and infection is considered to be the trigger." (PMID 40468431, 2025). "Anoxic symptoms such as tachypnea/dyspnea, fatigue/ decreased activity tolerance and cyanosis of lips are common manifestations of PH in patients with cblC deficiency, which are often induced by infection." (PMID 40468431, 2025).
peripheral neuropathy (1 paper, 2020). A disorder affecting the peripheral nervous system. "Peripheral neuropathy remains a classical but underdiagnosed complication of cblC defect." (PMID 33324334, 2020).
CBLC also shares sentences with these, for which no sentence is quoted: non-small cell lung carcinoma (4 papers); colorectal cancer (3); endometrial cancer (3); gastric cancer (2); myeloid neoplasm (2); propionic acidemia (2); thrombotic microangiopathy (2); acute kidney injury (1); acute myeloid leukemia (1); Anorexia (1); atypical hemolytic-uremic syndrome (1); biotinidase deficiency (1); carnitine deficiency (1); cervical cancer (1); chronic myelogenous leukemia (1); chronic myelomonocytic leukemia (1); colorectal adenoma (1); cor pulmonale (1); depression (1); dilated cardiomyopathy (1); epithelial malignant tumors (1); Failure to thrive (1); glutaric aciduria type I (1); hemolytic-uremic syndrome (1); hepatocellular carcinoma (1); Hypertension (1); Intellectual disability (1); interstitial lung disease (1); juvenile myelomonocytic leukemia (1); leukemia (1).
A further 16 diseases each share a sentence with CBLC in 1 paper.